LCN2 (lipocalin 2)
Diseases named in the same sentence as LCN2 in open-access papers (continued):
Sharing a sentence is not in itself a finding about the gene and the disease.
hepatocellular carcinoma (36 papers, 2014 to 2026). A malignant tumor that arises from hepatocytes. "In hepatocellular carcinoma, LCN2 levels are positively associated with differentiation, and metastasis is suppressed by LCN2." (PMID 40109857, 2025). "LCN2 plays a tumor-suppressive role by inducing EMT in ovarian carcinoma and hepatocellular carcinoma, where LCN2 levels are associated with well differentiation." (PMID 40109857, 2025). "Here, we focused on the role of LCN2 and the mechanism underlying its regulation by T3/TR in a hepatoma cell line." (PMID 25940797, 2015). "In hepatocellular carcinoma, LCN2 inhibits the transcriptional initiation of Twist1 to moderate EMT and suppress metastasis." (PMID 40109857, 2025). "By suppressing phosphoglycerate mutase 1 (PGAM1), the downregulation of lipocalin-2 (LCN2) promotes ferroptosis in hepatocellular carcinoma cells and facilitates the recruitment of CD8+ T cells." (PMID 39420203, 2024). "This inhibition also imparts resistance to sorafenib-induced ferroptosis on hepatocellular carcinoma cells by boosting the activity of the NF-κB/LCN2 (lipocalin 2) pathway." (PMID 39315094, 2024). "Another study further confirmed p-p65 promoted the expression of LCN2 to inhibit lipid peroxidation and finally diminished the ferroptosis in hepatocellular carcinoma." (PMID 37268653, 2023). "LCN2 has been previously shown to reversely regulate EMT via the LCN2/Twist signaling pathway in hepatocellular carcinoma." (PMID 32272958, 2020). "Another study reported that the knockdown of LCN2 increased the survival of hepatocellular carcinoma cells." (PMID 27168162, 2016). "On the other hand, LCN2 leads to apoptosis in leukemia cells and acts as a suppressor of proliferation and metastasis in hepatocellular carcinoma." (PMID 27912767, 2016). "Taken together, the data indicate that the migration phenotype in the T3-treated hepatoma cells can be restored in LCN2-KD conditions, but attenuated by a LCN2-neutralizing antibody." (PMID 25940797, 2015). "LCN2 was overexpressed in clinical hepatocellular carcinoma (HCC) patients, compared with normal subjects, and positively correlated with TRα levels." (PMID 25940797, 2015). "Accordingly, we conclude that LCN2 depletion reduces migration and invasion in J7 hepatoma cells, both in vitro and in vivo." (PMID 25940797, 2015). "The EMT-suppressive role of LCN2 has been found in hepatocellular carcinoma." (PMID 40109857, 2025). "Because LCN2 is a good candidate for hepatocellular carcinoma diagnosis and screening, the reduction of Lcn2 might indicate a beneficial development." (PMID 34954190, 2022). "However, LCN2 negatively modulates epithelial–mesenchymal transition (EMT) in hepatocellular carcinoma cells through the epidermal growth factor (EGF) or transforming growth factor (TGF)-β1/LCN2/Twist1 pathway." (PMID 34202288, 2021). "Moreover, LCN2 plays a protective role against the progression of hepatocellular carcinoma by suppressing cell proliferation and invasion, suggesting that the functionality of LCN2 depends on the condition analyzed." (PMID 32718038, 2020). "Further examination of whether the LCN2-mediated mechanism occurs in T3-regulated hepatoma cells revealed upregulation of p-Met and p-FAK after T3 stimulation in HepG2-TRα1 cells." (PMID 25940797, 2015). "T3-regulated LCN2 may play a role in hepatoma cell motility through activation of the Met/FAK cascade to promote metastasis." (PMID 25940797, 2015). "We validated a single-stranded, DNA aptamer-based, diagnostic method capable of detecting Lipocalin-2 (LCN2), a biomarker from clinically relevant hepatocellular carcinoma (HCC) patient serum, in the sandwich assay format." (PMID 26039737, 2015). "Furthermore, cytokine array and RNA sequencing analysis identified the LCN2 as a key factor in remodeling TME in the hepatocellular carcinoma (HCC)-on-a-chip model." (PMID 39188682, 2024).
hepatocellular carcinoma (continued). "Another study on hepatocellular carcinoma investigated the effect of LIFR, leukemia inhibitory factor receptor, in relation to Lcn-2." (PMID 37958332, 2023). "In xenograft tumors derived from hepatocellular carcinoma patients with low LIF receptor subunit alpha expression and high expression of LCN, an LCN2‐neutralizing antibody enhances the ferroptosis‐inducing and anticancer effects." (PMID 36655094, 2023). "The relationship between LCN2 and Twist1 has been previously reported that the LCN2/Twist1 signaling pathway negatively regulates EMT in hepatocellular carcinoma." (PMID 32272958, 2020). "For example, a study in hepatocellular carcinoma (HCC), a very aggressive primary liver cancer, performed ectopic expression of LCN2 in HCC cell lines (Chang liver and SK-Hep-1) and observed a significant inhibition in cell proliferation, migration, and invasion." (PMID 32575507, 2020). "In contrast, the function of LCN2 was previously shown to be exerted partly through blockage of the JNK and PI3K pathways in hepatocellular carcinoma cells." (PMID 27168162, 2016). "Thus, LCN2 appears to promote cell migration and invasion in SK-HEP1 hepatoma cells, both in vitro and in vivo." (PMID 25940797, 2015). "LCN2 is involved in the development of a variety of diseases: non-neoplastic diseases (such as cachexia, pneumonia, and kidney disease) as well as malignant tumors (such as hepatocellular carcinoma and pancreatic cancer)." (PMID 40109379, 2025). "The secretomes of cholangiocarcinoma cell lines specifically express lipocalin-2 (NGAL) and 49 other proteins that are not expressed by hepatocellular carcinoma cells." (PMID 36144640, 2022). "Regarding cholangiocarcinoma (CCA), a study reported that LCN2 expression was detected in the CCA cell line, HuCCA-1, but not in 4 hepatocellular carcinoma cell lines, HepG2, HCC-S102, SK-Hep-1, and Alexander, suggesting the expression might be specific to CCA." (PMID 24939880, 2014).
lung carcinoma (36 papers, 2008 to 2025). "Collectively, these findings establish LCN2 as a key molecule that is overexpressed in BM and is associated with poor clinical outcomes in patients with lung cancer." (PMID 41436606, 2025). "Recent research has shown that in the model of lung cancer cachexia, tissue-infiltrating neutrophils increase and secrete Lipocalin-2 (LCN2), inducing ferroptosis that causes tissue wasting." (PMID 39614322, 2024). "Samples of human lung cancer were used to identify the association between the serum lipocalin 2 (LCN2) level and cachexia progression." (PMID 36973755, 2023). "Recently, it has been reported that Lipocalin 2 is associated with radioresistance in oral cancer and lung cancer cells, and erlotinib resistance in NSCLC." (PMID 28088789, 2017). "Taken together, these results suggest that upregulation of ceruloplasmin, lipocalin 2 and perioston are associated with development of lung cancer, and correlated with repression of GPRC5A in NSCLC." (PMID 28088789, 2017). "Moreover, evaluation of lung cancer patients revealed an association between the serum LCN2 level and cachexia progression." (PMID 36973755, 2023). "Furthermore, treatment with the anti-LCN2 antibody alleviated the pathogenic phenotypes of lung cancer cachexia model mice, including the reduction in body weight and eWAT/iWAT wasting." (PMID 36973755, 2023). "Additionally, LCN2 overexpression has been associated with radioresistance in both oral cancer and lung cancer cells and can serve as a predictor of radioresistance." (PMID 33604288, 2020). "Pharmacological inhibition of IL-1R and STAT3 signaling effectively suppressed BM growth, highlighting the therapeutic potential of targeting the LCN2 axis in lung cancer brain metastasis." (PMID 41436606, 2025). "The secreted LCN2 plays a crucial role in inducing the ferroptosis and wasting of adipose and muscle tissues in lung cancer cachexia." (PMID 40313933, 2025). "To delineate the functional role of LCN2 in lung cancer brain metastasis, we first evaluated its expression across multiple lung cancer cell lines (A549, PC9, H358, H23, KLN205, LLC, and TC1)." (PMID 41436606, 2025). "In septic cardiac dysfunction and lung cancer cachexia, exogenous LCN2 induced ferroptosis via increasing the labile iron pool." (PMID 40109379, 2025). "In this study, we identified LCN2 as a pivotal factor predominantly expressed in lung cancer BM tumor cells, where it plays a crucial role in facilitating metastatic colonization." (PMID 41436606, 2025). "LCN2 overexpression correlates with tumor progression in multiple malignancies and serves as a cachexia biomarker in advanced lung cancer." (PMID 40636695, 2025). "Multiplex IHC staining of BM tissues from lung cancer patients confirmed the presence of activated astrocytes and macrophages in tumors with high LCN2 expression." (PMID 41436606, 2025). "Further investigations using small interfering RNA to silence LCN2 in OSCC cells and lung cancer cells revealed an increase in radiosensitivity, indicating that LCN2 defends cells against extracellular stimuli and facilitates cell survival." (PMID 39188682, 2024). "Further experiments revealed that the LCN2 induced ferroptosis in adipose tissue was responsible for tissue wasting in a mice model with lung cancer cachexia." (PMID 38035773, 2024). "Taken together, these findings suggested that myeloid-derived LCN2 contributed specifically to the ferroptotic tissue wasting observed in lung cancer cachexia model mice." (PMID 36973755, 2023). "Antibody depletion of TI-Neu, as well as myeloid-specific-knockout of Lcn2, prevented ferroptosis and tissue wasting in experimental models of lung cancer cachexia." (PMID 36973755, 2023). "Increased LCN2 in lung cancer promotes iron efflux, thereby avoiding iron accumulation and ferroptosis." (PMID 38072118, 2023).
lung carcinoma (continued). "We also conducted flow-cytometry analyses of the eWAT, iWAT, and Gast from LLC lung cancer cachectic model mice: TI-Neu cells, macrophages, and MDSCs all expressed LCN2 protein." (PMID 36973755, 2023). "Collectively, the findings from studies on myeloid-specific knockout and therapy with anti-LCN2 antibody demonstrated that targeted elimination of LCN2 alleviated ferroptosis and tissue wasting significantly in mice with lung cancer cachexia." (PMID 36973755, 2023). "Given our findings regarding LCN2 knockout, next we explored if treating mice with an anti-LCN2 antibody to achieve targeted elimination of LCN2 conferred similarly protective effects in lung cancer cachexia model mice." (PMID 36973755, 2023). "Next, we examined the impact of knocking out LCN2 by generating myeloid-specific Lcn2 knockout (Lcn2f/fLysMcre) mice and inducing lung cancer cachexia in these mice and their control (Lcn2f/+LysMcre) littermates." (PMID 36973755, 2023). "Collectively, these findings implied that the pathological changes which affected the wasting tissues of lung cancer cachexia models were related to the increased LCN2 level observed in lung cancer patients suffering from cachexia." (PMID 36973755, 2023). "Protein expression of LCN2 was higher in the wasting adipose tissue and muscle tissues of experimental mouse models of lung cancer cachexia." (PMID 36973755, 2023). "Until this point, we had focused on the nature of the aberrantly high LCN2 level in lung cancer cachexia model mice and LCN2-mediated induction of ferroptosis in wasting tissues." (PMID 36973755, 2023). "Biochemical analysis showed that lung cancer cachexia model mice treated with anti-LCN2 antibody had significantly lower Fe2+ and MDA concentrations in their eWAT, iWAT, and Gast than those in controls." (PMID 36973755, 2023). "A proteomics-based analysis of the profiles of serum protein factors in lung cancer cachectic mice showed significantly higher LCN2 levels in cachectic mice than in control animals." (PMID 36973755, 2023). "Pan-cancer studies found that LCN2 expression is increased in lung cancer, breast cancer, and other tumors." (PMID 38072118, 2023). "Elevated LCN2 expression has been observed in various human solid tumours, including breast, colorectal, ovarian, gastric, ovarian, bladder, kidney, and lung cancers, in addition to ESCC." (PMID 37753805, 2023). "The expression level of Lipocalin-2 in peripheral blood serum of patients with lung cancer was significantly higher than that of healthy people, and the difference was statistically significant (P < 0.001)." (PMID 33626852, 2021). "Lipocalin-2 is highly expressed in serum of patients with lung cancer, which is related to pathological differentiation, stage and lymph node metastasis." (PMID 33626852, 2021). "The expression of Lipocalin-2 in patients with lung cancer was related to the differentiation, stage and lymph node metastasis of pathological tissues, and the difference was statistically significant (P < 0.05)." (PMID 33626852, 2021). "A previous study has demonstrated that LCN2 is upregulated in lung cancer cells treated with X-ray irradiation and the sensitivity of these lung cancer cells to radiation is enhanced by the silencing of LCN2." (PMID 33604288, 2020). "We also observed the expression of HK2, LCN2 and autophagy-related genes in lung cancer cell lines, including CL1-0, CL1-5, TL-6 and H1975 with or without 0.25 mM NiCl2." (PMID 29285270, 2017). "Taken together, our study suggests that ceruloplasmin, lipocalin 2 and periostin are potential candidate biomarkers at early stages for lung cancer." (PMID 28088789, 2017). "We also delineated the functional significance of the IL-1β–LCN2 axis in lung cancer BM." (PMID 41436606, 2025). "To investigate whether LCN2 specifically contributes to lung cancer BM, we established both subcutaneous and orthotopic pulmonary tumor models." (PMID 41436606, 2025).
lung carcinoma (continued). "These mechanistic insights suggest that LCN2 may serve as both a therapeutic target and a prognostic biomarker in lung cancer brain metastasis." (PMID 41436606, 2025). "Despite uncovering the central role of LCN2 in lung cancer BM, our study has several limitations." (PMID 41436606, 2025). "The serum levels of Lipocalin-2 in 60 lung cancer patients and 63 healthy people were detected by enzyme-linked immunosorbent assay (ELISA), and the relationship between the expression level of Lipocalin-2 and the clinical characteristics of lung cancer was analyzed." (PMID 33626852, 2021). "Therefore, the aim of this study was to investigate the expression level of Lipocalin-2 and its clinical significance in serum of patients with lung cancer." (PMID 33626852, 2021). "Lipocalin 2 was also found to induce apoptosis under ER stress in lung cancer cells." (PMID 32093767, 2020). "Both HK2 and LCN2 serve as biomarkers in lung cancer progression." (PMID 29285270, 2017). "In lung cancer, LCN2 protein level increases significantly after X-ray irradiation, suggesting that overexpression of LCN2 might contribute to radiation resistance in cancer cells." (PMID 25476483, 2015). "The expression of LCN2 in oral squamous cell carcinoma (OSCC) cells and lung cancers was significantly upregulated by X-ray irradiation, possibly involved in PI3K/Akt pathway." (PMID 39188682, 2024). "Although granulocytes in the lung cancer BM TME may also contribute to LCN2, tumor-specific knockdown of LCN2 markedly reduces macrophage infiltration and the metastatic burden." (PMID 41436606, 2025). "Moreover, Kaplan‒Meier analyses of public datasets revealed that high LCN2 mRNA levels predict worse event-free survival (EFS) and overall survival (OS) in lung cancer patients." (PMID 41436606, 2025). "This approach revealed aberrantly higher LCN2 levels in lung cancer patients with cachexia than in non-cachectic lung cancer patients or healthy controls." (PMID 36973755, 2023). "Induction of lung cancer cachexia led to the expected increase in protein expression of LCN2 in the serum of Lcn2f/+LysMcre mice, but not in Lcn2f/fLysMcre mice." (PMID 36973755, 2023). "Consistent with our data on the profiles of protein factors, ELISA results showed that serum concentrations of LCN2 were higher in cachectic lung cancer patients than in non-cachectic lung cancer patients or healthy controls." (PMID 36973755, 2023). "Collectively, these results indicate that LCN2 facilitates cross-talk between tumor cells and astrocytes in the brain, activating astrocytes to secrete CCL2, thereby promoting macrophage recruitment and contributing to a protumorigenic microenvironment in the BM of lung cancer patients." (PMID 41436606, 2025). "Notably, using both in vitro assays and in vivo models of carotid artery and left ventricular injection, we found that LCN2-induced astrocyte activation does not compromise BBB integrity in BM from patients with lung cancer." (PMID 41436606, 2025). "In our study, STAT3 inhibition was effective in the PC9-BM model but not in the A549 model, suggesting that LCN2 expression may serve as a predictive biomarker for STAT3-targeted therapy in lung cancer BM." (PMID 41436606, 2025). "Similarly, the serum concentration of LCN2 in lung cancer patients with cachexia was higher than those without cachexia and was negatively related to BMI and serum albumin levels in these patients." (PMID 38035773, 2024). "Additionally, although increased LCN2 expression was shown to correlate with the apoptosis induced by several reagents in human lung cancer cells, this LCN2 upregulation represented a survival rather than a proapoptotic response." (PMID 33604288, 2020). "However, the expression levels of Cp, LCN2, and Postn are relatively high in most of lung cancer cell lines including HCC827, H1792, H1975, and H661, but not in Calu-1 and A549." (PMID 28088789, 2017).